AREG (amphiregulin)
Diseases named in the same sentence as AREG in open-access papers (continued):
Sharing a sentence is not in itself a finding about the gene and the disease.
colorectal cancer (32 papers, 2009 to 2026). A primary or metastatic malignant neoplasm that affects the colon or rectum. "Elevated AREG expression is commonly observed in colorectal cancer and has been associated with poorer prognosis and resistance to anti-EGFR monoclonal antibodies such as cetuximab and panitumumab." (PMID 41515404, 2025). "So germane is the role of amphiregulin that it has been proposed as a prognostic marker in malignant colorectal cancers, and it is associated with chemotherapy resistance." (PMID 36982582, 2023). "For genes associated with colorectal cancer cells, only the expression of AREG was significantly up-regulated by BLE IC50 and GA IC50, by 3.97 and 2.21 folds respectively." (PMID 32561807, 2020). "The expression of selected genes related to MG degradation III (AKR1B10, AKR1C2 and ADH4), glyoxalase system (GLO1 and HAGH), glucose transport (SLC2A1 and SLC5A1) and colorectal cancer-associated genes (AREG, CXCL8 and CEACAM1) were quantitated using qRT-PCR." (PMID 32561807, 2020). "In colorectal cancer patients, AREG expression in particular has been repeatedly associated with an enhanced responsiveness to cetuximab, especially for KRAS wild-type tumours." (PMID 27933395, 2017). "However, in colorectal cancer patients receiving cetuximab, high gene expression of epiregulin and amphiregulin in tumour was associated with better outcome." (PMID 19127259, 2009). "The chelates ferric citrate and ferric EDTA induce the oncogenic growth factor amphiregulin (a positively associated risk factor with colorectal cancer) and it should now be determined whether the ferrous sulfate impact on Wnt pathways in vitro translates to an oncogenic risk in vivo." (PMID 29682205, 2018). "AREG KO NK showed a mild increase in lysis of the liver cancer cell line HepG2 and the colorectal cancer cell line HCT116." (PMID 41082397, 2026). "Serum levels of AREG were higher in 41 patients with colorectal cancer (stage IV or recurrent group, median = 31.55 pg/mL) than in the stage I–III group (78 patients, median = 15.48 pg/mL)." (PMID 40422206, 2025). "This was motivated by the low response rates of human EOC to ICIs (<10%) and the reported ability of high AREG levels to predict response of colorectal cancer patients to anti-EGFR antibodies." (PMID 40666944, 2025). "AREG, an epidermal growth factor receptor (EGFR) ligand, is upregulated in colorectal cancer (CRC) tissue and is associated with tumor invasion depth, nerve infiltration, and liver metastasis." (PMID 39683442, 2024). "The involvement of amphiregulin in oncogenic progression in humans has been observed in common cancers, including lung, breast, ovarian, and colorectal cancers." (PMID 36982582, 2023). "AREG has also been previously reported to be increased in a human colorectal cancer cell line treated with secondary bile acids or salts such as deoxycholic acid but not the primary bile acid cholic acid." (PMID 36142285, 2022). "Our in vitro study also indicated that AREG significantly enhanced the growth of cetuximab-sensitive RAS/BRAF wild-type colorectal cancer cell lines with increased phosphorylation of AKT and ERK1/2." (PMID 34893673, 2021). "This study showed that CCL20-dependent proliferation of colorectal cancer cells was dependent on amphiregulin secretion and EGFR phosphorylation through an ERK-mediated process." (PMID 34853656, 2021). "Of the remaining inflammatory proteins, those that showed the strongest potential as future colorectal cancer biomarkers were AREG, LRG1 and potentially MIC-1/GDF15." (PMID 34503217, 2021). "High EREG and AREG expressions are a predictive marker for panitumumab therapy benefit on PFS in RAS wild-type advanced colorectal cancer patients." (PMID 32587640, 2020). "Retrospective comparison of colorectal cancer patients treated with anti-EGFR revealed that AREG expression is better than AREG gene methylation to predict clinical follow-up." (PMID 31370270, 2019).
colorectal cancer (continued). "Amphiregulin, a ligand of the epidermal growth factor receptor (EGFR), is associated with the efficacy of cetuximab, an antibody against EGFR, as treatment for colorectal cancer (CRC)." (PMID 26569500, 2015). "Our study confirms published data on the prognostic/predictive significance of BRAF, KRAS mutations and on the tumour expression of AREG, EREG mRNA in cetuximab-treated patients with colorectal cancer." (PMID 23374602, 2013). "Other potential biomarkers of cetuximab activity in colorectal cancer include EGFR ligands (epiregulin and amphiregulin) and polymorphisms in EGFR, EGF, and Fc fragment of IgG receptor." (PMID 19127259, 2009). "EGFR and its ligands EREG and AREG are commonly overexpressed in colorectal cancer." (PMID 37974093, 2023). "PGE2 promotes amphiregulin expression and plays an essential role in colorectal cancer progression." (PMID 36982582, 2023). "Our results indicated that high baseline plasma AREG levels could predict PFS after first-line cetuximab plus FOLFIRI chemotherapy in patients with RAS/BRAF wild-type colorectal cancer." (PMID 34893673, 2021). "In colorectal cancer, AREG is known to act competitively with anti-EGFR monoclonal antibodies and activate downstream signaling, and thus may be involved with cetuximab resistance." (PMID 34893673, 2021). "In contrast, in the present study, AREG-induced cetuximab resistance may be attributed to direct EGFR activation in RAS/BRAF wild-type colorectal cancer." (PMID 34893673, 2021). "Recently, several studies have reported that AREG (and EREG) expression was associated with the likelihood of liver metastasis in colorectal cancer, and suggested that it might play an important role in the development of liver metastasis." (PMID 22409860, 2012). "In the case of cetuximab treatment of colorectal cancer, which targets another receptor of the ERBB-family (the epidermal growth factor receptor) the expression of receptor ligands (i.e. amphiregulin and epiregulin), as well KRAS mutation, predict treatment response." (PMID 22014070, 2011). "Amphiregulin (AREG), a principal ligand of the epidermal growth factor receptor (EGFR, also known as ErbB1), plays a critical role in colorectal carcinoma by driving tumor cell proliferation, survival and resistance to therapy." (PMID 41515404, 2025). "Amphiregulin, an EGFR ligand, is present on colorectal cancer cell-derived exosomes, and exosomal amphiregulin has been shown to be five-fold more effective in stimulating cell invasiveness than the soluble ligand." (PMID 32751440, 2020). "Expression of the epidermal growth factor ligands amphiregulin (AREG) and epiregulin (EREG) is positively correlated with a response to EGFR-targeted therapies in colorectal cancer." (PMID 31370270, 2019). "Amphiregulin (AREG) and epiregulin (EREG), which are ligands of EGFR, are overexpressed in colorectal cancer at both the mRNA and protein levels." (PMID 27344184, 2016). "Epidermal growth factor receptor (EGFR) and its ligands amphiregulin (AREG) and epiregulin (EREG) play a central role in the development of colorectal cancer, but the prognostic values of AREG and EREG are controversial." (PMID 27344184, 2016). "In this study, modest correlations of AREG and EREG relative mRNA expression were observed between primary colorectal cancer and corresponding liver metastases." (PMID 22409860, 2012). "Amphiregulin (AREG) and Epiregulin (EREG), ligands of EGFR, are reported to be predictive biomarkers of colorectal cancer patients treated with Cetuximab, an anti-EGFR antibody." (PMID 22409860, 2012). "Recently, two large studies on AREG and EREG expression in patients with colorectal cancer who received Cetuximab were published." (PMID 22409860, 2012). "The purpose of this study is to determine the correlation of AREG and EREG expression between primary colorectal cancer and corresponding liver metastases." (PMID 22409860, 2012).
colorectal cancer (continued). "AREG reversed the inhibitory effects of cetuximab in RAS/BRAF wild-type cetuximab-naïve colorectal cancer cells, but not in cetuximab-resistance cells in vitro." (PMID 34893673, 2021). "It is still controversial whether AREG protein or mRNA expression levels are prognostic factors in patients with colorectal cancer who did not undergo cetuximab- or panitumumab-based chemotherapy." (PMID 34893673, 2021). "Administration of exogeneous TGF-α and amphiregulin did not induce migration of the colorectal cancer cell lines, while blocking TGF-α and amphiregulin action did not diminish the effects of CCL20 in inducing CCL20 secretion or proliferation." (PMID 34853656, 2021).
lung cancer (31 papers, 2010 to 2025). A malignant neoplasm involving the lung. "In Timer 2.0 analysis, progressively higher AREG expression among lung cancer patients was associated with correspondingly lower overall survival rates." (PMID 38904011, 2024). "Serum Amphiregulin levels are associated with reduced survival in lung cancer patients." (PMID 39199549, 2024). "Moreover, AREG is linked to a worse prognosis and shorter survival in lung cancer patients." (PMID 38904011, 2024). "Various in vivo and in vitro studies demonstrated that amphiregulin exacerbates lung cancer cell proliferation and tumor growth by stimulating the EGFR family members to activate their downstream pathways." (PMID 39858622, 2025). "In several cancers (ovarian, breast, and lung cancers), high AREG expression correlates with a worse prognosis 31-33." (PMID 38904011, 2024). "Our analysis of RNA sequencing data identified that long-term exposure to PM upregulates AREG expression in lung cancer cells." (PMID 38904011, 2024). "AREG overexpression has been demonstrated in a wide variety of human lung cancer tissues, and AREG is assumed to play an important role in promoting lung cancer proliferation." (PMID 38904011, 2024). "We observed that PM increases AREG-dependent lung cancer proliferation through glutamine metabolism." (PMID 38904011, 2024). "In conclusion, our study results demonstrate that long-term exposure to PM increases AREG expression in lung cancer cells." (PMID 38904011, 2024). "To examine the effects of AREG levels on lung cancer progression, we investigated the clinical significance of AREG identified in lung adenocarcinoma samples from the TCGA database." (PMID 38904011, 2024). "AREG-induced IL-8 production in a human lung cancer cell line (A549) via pathways involving EGFR, PI3K/AKT, and ERK." (PMID 37868614, 2023). "Given its unique role in lung morphogenesis, amphiregulin plays a decisive role in lung cancer by stimulating autocrine growth and the suppression of apoptosis." (PMID 29254206, 2017). "We also analyzed a collection of lung cancer cells which tend to express elevated levels of amphiregulin, too." (PMID 21967738, 2011). "PM augments AREG-dependent lung cancer proliferation through increasing glutamine metabolism." (PMID 38904011, 2024). "In the future, whether to use EGFR inhibitors such as erlotinib (Tarceva®) and gefitinib (Iressa®) for targeting AREG and decreasing long-term exposure to PM-induced lung cancer patients is worthy of further study." (PMID 38904011, 2024). "In future studies, using intratracheal instillation in vivo model, which more closely mimics natural exposure to PM, can be employed to more clearly explore how long-term exposure to PM increases the expression of AREG and promotes lung cancer growth through glutamine metabolism." (PMID 38904011, 2024). "AREG stimulates cell migration and proliferation while reducing lung cancer cell apoptosis." (PMID 38904011, 2024). "AREG also promotes tumor growth in pancreatic, colorectal, liver, and lung cancers 41-43." (PMID 38904011, 2024). "Moreover, studies in melanoma, as well as gastric and lung cancer have similarly observed that AREG leads to immunosuppression through the regulation of Treg function." (PMID 38831884, 2024). "Our results suggest that targeting AREG could be a valuable therapeutic approach for lung cancer exposed with PM." (PMID 38904011, 2024). "Additionally, Tu and colleagues demonstrated that incense smoke can sensitize lung cancer cells to epidermal growth factor receptor (EGFR) tyrosine kinase inhibitors (TKIs) by inducing amphiregulin (AREG) expression." (PMID 39725665, 2024). "Therefore, AREG plays a crucial role in regulating lung cancer cell growth, differentiation, and metastasis." (PMID 38904011, 2024). "Furthermore, increased expression of AREG and AURKA in lung cancer cells has been associated with resistance to gefitinib treatment." (PMID 35216325, 2022).
lung cancer (continued). "It would be interesting if these EGFR ligands such as TGF-alpha, amphiregulin or epiregulin, might serve as biomarker in head and neck or lung cancer patients as we found for EGF." (PMID 34115785, 2021). "To validate whether the amount of AREG secreted from lung cancer cells affects cell proliferation, we found that long-term exposure to PM promotes lung cancer AREG protein expression, which is significantly decreased when transfected with AREG shRNA, as determined by western blot assay." (PMID 38904011, 2024). "Our results illustrate that targeting AREG might offer a novel treatment approach for lung cancer." (PMID 38904011, 2024). "Of note, AREG, EREG, FOSL1, MYC, and PLAU are involved in the EGFR signaling pathway, which is a key pathway in lung cancer development." (PMID 39858622, 2025). "For example, induction of AREG expression sensitizes lung cancer cells to EGFR TKI and increases the tumorigenic dependence of non-small cell lung cancer on the AREG-induced EGFR signaling pathway, thus enhancing the progression of NSCLC." (PMID 36186485, 2022). "First, we compared the mRNA levels of common EGFR ligands in lung cancer (HB-EGF, EGF, TGF-α, BTC, AREG, and EREG) by using the gene expression dataset GSE30219, GSE3141, and GSE50081." (PMID 36439487, 2022). "Targeting of AREG has been considered for other cancers, for example AREG siRNAs reduced EGFR activation in hepatocellular carcinoma cell lines and lung cancer cells, which led to decreased growth and increased sensitivity to anti-EGFR targeted therapy." (PMID 35993275, 2022). "In human lung cancer, EREG and AREG mRNA or protein levels are elevated in a subset of NSCLC cell lines as well as NSCLC specimens and predict poor survival." (PMID 30412601, 2018). "In NSCLC, EGFR is upregulated and amphiregulin (AREG), an EGFR ligand, is packaged in exosomes derived from lung cancer cells." (PMID 29720982, 2018). "The decrease of AREG levels in CRL-2868 cells inhibited the accumulation of this molecule into exosomes, reverting the effects on osteoclastogenesis induced by lung cancer exosomes." (PMID 28600504, 2017). "ADAM17 can shed amphiregulin, transforming growth factor α and other EGFR ligands, it can also activate the EGFR to thereby improve the lung cancer cell proliferation and cell motility capacity." (PMID 25351873, 2015). "ADAM17 has been shown to shed ligands of EGFR, such as amphiregulin and TNFα, and subsequently activate EGFR, thereby improving the proliferation and migration of lung cancer cells." (PMID 25364437, 2014). "AREG, in turn, upregulates the glutamine transporter SLC1A5 and promotes the accumulation of glutamine-derived TCA cycle metabolites via the EGFR/PI3K/AKT/mTOR signaling pathway, thereby promoting lung cancer cell growth and proliferation." (PMID 38904011, 2024). "To determine how frequently ligands that initiate signaling of both pathways are found in lung cancer, we analyzed serum for hepatocyte growth factor (HGF), transforming growth factor-alpha, and amphiregulin (AREG) in lung cancer cases and tobacco-exposed controls." (PMID 21390244, 2010). "In addition, depletion of iRhoms induced a similar decrease in amphiregulin release in the KRAS mutant NSCLC cells lines NCI-H358 and NCI-H1792, demonstrating the conserved function of iRhoms in promoting growth factor signalling in lung cancer cell lines." (PMID 35971826, 2022). "Given the importance of EGFR signaling as a therapeutic target in lung cancer, further examination of the effect of EGF, heregulin, and amphiregulin on GPER expression and function in lung cancer may provide new insights into resistance to EGFR inhibitors and or how estrogens stimulate lung cancer." (PMID 23273253, 2012). "Additionally, in vitro studies have also found increased AREG expression/secretion in radiation-resistant pancreatic cancer cells and cisplatin-resistant breast and hepatoma cancer cells but not in cisplatin-stimulated lung cancer cells." (PMID 39452130, 2024).
lung cancer (continued). "Notably, the effect of ABL kinase inhibition on MMP9 secretion appears to be selective as secretion of amphiregulin (AREG), which is markedly enhanced by co-culture of MSCs with lung cancer cells, was not decreased by treatment with either GNF5 or ABL001." (PMID 33119681, 2020).